CXCL16 (C-X-C motif chemokine ligand 16)
Diseases named in the same sentence as CXCL16 in open-access papers (continued):
Sharing a sentence is not in itself a finding about the gene and the disease.
psoriasis (continued). "With the development of the pathogenesis of psoriasis, the role of IL-17, IL-23, CXCL16, CXCL17 and tumor necrosis factor-α (TNF-α) in the immunoinflammatory process of psoriasis is becoming clear." (PMID 35693833, 2022). "RT-qPCR experiments further confirmed that CXCL16 expression was significantly elevated in MDMs from psoriasis patients compared to healthy controls, while no statistical differences were observed for CXCL1, CXCL3, and CXCL5." (PMID 40722833, 2025). "Studies have shown that CXCL16 has chemotactic effects on CD4+ T cells, and further activates CD8+ T cells, thereby promoting the secretion of IFN-γ, IL-17 and TNF-α, etc., and is involved in the pathogenesis of psoriasis progress." (PMID 35693833, 2022). "Lastly, although RT-qPCR confirmed increased CXCL16 expression in MDMs from psoriasis patients, there is a lack of tissue-based spatial transcriptomics or protein-level validation, and the efficacy of CXCL16 blockers in preclinical models has not been evaluated." (PMID 40722833, 2025).
Arthritis (9 papers, 2013 to 2024). Inflammation of a joint. "Moreover, CXCL16 blockade or CXCR6 deficiency led to reduced features of arthritis and lower IL-17 production in experimental models." (PMID 38405187, 2024). "We also detected significantly more Id1 in RA compared to OA and other arthritis SFs by ELISA, which correlates highly with Chemokine (C-X-C motif) ligand 16 (CXCL16) levels." (PMID 24620998, 2014). "We showed that deletion of CXCR6 (the only known receptor for CXCL16) prevents arthritis development, severity and joint tissue vascularity in mice in response to K/BxN serum." (PMID 24620998, 2014). "Indeed, genetic CXCR6 deficiency is protective in mouse models of arthritis, and antibody-mediated blockade of CXCR6 or CXCL16 ameliorates disease in a mouse model of MS." (PMID 39087473, 2024). "Taken together, clonotypes and trafficking analyses of T cells suggested that SF CXCR3hi CXCR6hi/lo effector CD8+ T cells, recruited via CXCL9/10/11 and CXCL16 secreted by myeloid cells, may contribute to arthritis-irAE disease pathogenesis." (PMID 35413951, 2022). "Subsequently, miR-451 downregulates the expression of CXCL16 in monocytes and reduces the inflammatory milieu in the preclinical phase of RA, thereby attempting to delay the shift from the preclinical phase to the clinical manifestation of arthritis." (PMID 33633196, 2021). "Interestingly, studies demonstrated that NFKBIZ mediated IL-6 production, ADRB2 antagonists reduced the severity of arthritis, and that anti-CXCL16 antibody inhibited infiltration of inflammatory cells and arthritis." (PMID 23936839, 2013).
liver fibrosis (8 papers, 2019 to 2025). "To explore the mechanisms underlying the beneficial effects of QGHXR on liver fibrosis, we studied the CXCL16/CXCR6 axis in ethanol plus CCl4-treated mice following QGHXR administration." (PMID 36636609, 2023). "The current study showed that ethanol feeding and CCl4 injection resulted in increased serum CXCL16 concentrations and upregulated hepatic CXCL16 mRNA and protein expression, suggesting the involvement of CXCL16 in the development of liver fibrosis." (PMID 36636609, 2023). "Increased hepatic CXCL16 mRNA expression was found in patients with liver fibrosis compared to controls." (PMID 36636609, 2023). "We found that QGHXR alleviated liver injury, hepatic steatosis, and hepatic fibrosis and downregulated CXCL16 expression in ethanol plus CCl4-induced liver fibrosis." (PMID 36636609, 2023). "Then, we focused on the influence of CXCL16 treatment on the QGHXR-induced protective effects in liver fibrosis." (PMID 36636609, 2023). "NKT cells drive hematopoietic stem cell activation and liver fibrosis by stimulating CXCL16 in chronic liver injury." (PMID 36636609, 2023). "Previous report has demonstrated that CXCL16/CXCR6 signaling pathway promotes the progression of liver fibrosis." (PMID 31379980, 2019). "This study demonstrated that QGHXR mitigates experimental alcoholic liver fibrosis by CXCL16 inhibition, and may be considered a potential therapeutic agent for treating liver fibrosis." (PMID 36636609, 2023). "Consistent with the in vitro results, QGHXR intervention robustly decreased CXCL16 levels in the serum and liver of ethanol-fed mice injected with CCl4, indicating that the reduced CXCL16 level is partially attributed to QGHXR-induced protective effects in experimental liver fibrosis." (PMID 36636609, 2023). "Several studies have emphasized the crucial role of CXCL16 in the progression of liver fibrosis." (PMID 36636609, 2023). "Our results reveal the potential mechanism underlying QGHXR-induced antifibrotic effects and suggest that CXCL16 could serve as a novel target for the treatment of liver fibrosis." (PMID 36636609, 2023). "CXCL16 is highly expressed in patients with hepatic fibrosis." (PMID 36636609, 2023). "However, further study is needed to explore the role of FASLG signaling pathway and CXCL and CCL signaling pathway(Cxcl16-Cxcr6, Ccl6-Ccr2 and Ccl5-Ccr5) in liver fibrosis of schistosomiasis." (PMID 36618421, 2022). "NKT cells and CXCL and CCL signaling pathway such as Cxcl16-Cxcr6, Ccl6-Ccr2 and Ccl5-Ccr5 might be potential targets to alleviate hepatic fibrosis of schistosomiasis." (PMID 36618421, 2022). "On the other hand, liver NKT cells accumulate in a CXCR6-dependent manner early after injury, exacerbating the inflammatory response and promoting the progression of liver fibrosis, suggesting that the CXCR6/CXCL16 pathway may be an effective target for the treatment of liver fibrosis." (PMID 38846640, 2024). "Therefore, in this study, we treated mice with QGHXR to determine whether QGHXR could protect against ethanol + CCl4-induced liver fibrosis in a CXCL16-dependent manner." (PMID 36636609, 2023). "Although CXCL16 exists as a crucial role in the progression of liver fibrosis, the role of CXCL16 in QGHXR-mediated antifibrotic effects has not yet been elucidated." (PMID 36636609, 2023). "Kupffer cells produce CXCL16, attracting NKT cells promoting progression of liver fibrosis." (PMID 36013073, 2022).
papillary thyroid cancer (8 papers, 2016 to 2025). "miR-873-5p regulates the invasive process of papillary thyroid carcinoma cells by targeting CXCL16, which has a structural domain of a chemokine." (PMID 40442738, 2025). "mir-873-5p inhibit the invasion of papillary thyroid cancer cells by interfering with the expression of CXCL16." (PMID 38693503, 2024). "The aim of this study was to investigate the molecular characteristics of CXCL16-expressing papillary thyroid cancers (PTCs) and to explore the therapeutic potential of targeting CXCL16 in PTCs." (PMID 31527616, 2019). "The aim of this study was to investigate the molecular characteristics of CXCL16-expressing papillary thyroid cancers (PTCs)." (PMID 31527616, 2019). "High CXCL16 expression was associated with aggressive pathologic phenotypes, the higher TNM staging and lymph node metastasis in 77 patients with papillary thyroid cancers, in 25 patients with thyroid follicular adenomas, and 81 - with normal thyroid tissues from the SNUH cohort." (PMID 36686729, 2022). "CXCL16 has been shown to have a pro-tumoral function in papillary thyroid cancer (PTC)." (PMID 36686729, 2022). "Also, increased CXCL16 expression enhances the proliferation of papillary thyroid cancer TPC-1 and K-1 cells." (PMID 33800554, 2021). "It has been shown that overexpression of CXCL16 enhances the proliferation of TPC-1 and K-1 papillary thyroid cancer cells." (PMID 37272931, 2023).
acute coronary syndrome (7 papers, 2012 to 2025). Signs and symptoms related to acute ischemia of the myocardium secondary to coronary artery disease. "For instance, CXCL16 was found to be associated with long-term mortality after adjustment for other risk factors in patients with acute coronary syndrome." (PMID 24489966, 2014). "CXCL16 is an inflammation marker, expressed by numerous cell types and is associated with atherosclerosis, and acute coronary syndromes in humans." (PMID 25152735, 2014). "CXCL16 is upregulated upon platelet activation and in acute coronary syndrome." (PMID 25152735, 2014). "Soluble C-X-C chemokine ligand 16 (CXCL16), a scavenger receptor for oxidized low density lipoprotein, has been shown to promote atherogenic effects in vivo and to predict long-term mortality in acute coronary syndrome." (PMID 24489966, 2014).
coronary artery disease (7 papers, 2013 to 2025). "The CXCL16 gene polymorphism rs3744700 is closely related to coronary heart disease and can increase the risk of coronary heart disease." (PMID 35668739, 2021). "In cardiovascular research, serum CXCL16 levels have been positively correlated with the severity of coronary artery disease, highlighting its potential as a biomarker for cardiovascular risk assessment." (PMID 41357074, 2025). "CCL3, CCL18, CXCL12/SDF-1, CXCL16, IGF1 and IL10 have been linked to pro-angiogenesis and/or coronary artery diseases." (PMID 23496821, 2013). "This could explain the in creased incidence of coronary artery disease (CAD) in those patients and the close relationship between CAD and increased levels of CXCL16." (PMID 33312065, 2020).
Crohn disease (7 papers, 2013 to 2025). A gastrointestinal disorder characterized by chronic inflammation involving all layers of the intestinal wall, noncaseating granulomas affecting the intestinal wall and regional lymph nodes, and transmural fibrosis. "Current clinical studies have revealed that there are high-profile inflammatory markers in subjects with Crohn’s disease, specifically activated monocyte/macrophage-associated markers such as IL-1β and chemokine CXCL16." (PMID 40806424, 2025). "Specifically, the activated monocyte/macrophage-associated markers IL-1β and CXCL16 were declined post-treatment, highlighting the potential of Stem Cell Educator therapy for the clinical management of patients with Crohn’s disease." (PMID 40806424, 2025). "Genotypic and allelic distribution of CXCL16 rs2277680 polymorphism in Malaysian Crohn’s disease (CD) patients and control individuals." (PMID 27069792, 2016). "Previously, increased intestinal CXCL16 expression has been observed in the colonic biopsies of Crohn ́s disease patients due to immune cell infiltration." (PMID 23844808, 2013). "Previously, CXCL16 was shown as a unique marker for Crohn's disease, and our data suggest that CXCL16 may also be important in the pathogenesis of EoE." (PMID 25505954, 2014).
diabetic nephropathy (7 papers, 2014 to 2024). "In support of clinical relevance of these observations in experimental animal models, clinical studies have shown that circulating CXCL16 is elevated in patients with CKD and diabetic nephropathy and high levels of CXCL16 are associated with CKD progression and development of proteinuria." (PMID 26941655, 2016). "CXCL16 has previously been described to be elevated in patients with urothelial cancer and diabetic kidney disease." (PMID 38779086, 2024). "In the present study, we point to a new pathological manifestation of CXCL16 in the context of diabetic nephropathy." (PMID 24489966, 2014). "Similarly, CXCL16 promotes inflammatory markers and infiltrated cell factors, and reduces antioxidants, subsequently accelerating diabetic nephropathy development." (PMID 35335970, 2022). "Similarly, regulation of CXCL16 and ADAM10 expression is considered to be an early response in diabetic nephropathy development." (PMID 35335970, 2022).
lupus nephritis (7 papers, 2012 to 2025). Glomerulonephritis in the context of systemic lupus erythematosus. "In addition, increased CXCL16 was found in the urine of patients with lupus nephritis and was significantly associated with urinary protein levels as well as activity index and score of systemic lupus erythematosus." (PMID 24460887, 2014). "Increased urinary levels of CXCL16 have been observed in patients with acute tubular necrosis and lupus nephritis." (PMID 33573220, 2021). "Additionally, CCL-11, CXCL13, and CXCL16 are associated with disease activity, while serum IL-8, CCL17, CXCL16, and CX3CL1 are linked specifically to active lupus nephritis." (PMID 40095875, 2025). "The increase of urinary CXCL16 has been detected in patients with acute tubular necrosis or with lupus nephritis, revealing that CXCL16 could be a useful biomarker for these diseases." (PMID 30460232, 2018). "CXCL16, MCP-1, and VCAM-1 levels were measured in urine samples from 74 lupus nephritis patients and 13 healthy volunteers." (PMID 22788914, 2012).
Sepsis (7 papers, 2021 to 2026). Sepsis is defined as life-threatening organ dysfunction caused by a dysregulated host response to infection. "For example, the CXCL16 T123V181 haplotype is associated with an increased risk of sepsis morbidity and a higher MOD score." (PMID 40050290, 2025). "The improved multiplex ligation detection reaction (iMLDR) method was employed in the genotyping and genetic association analyses to determine the associations between CXCL16 haplotypes and sepsis morbidity rate and higher MOD scores in three cohorts." (PMID 34539750, 2021). "Our findings provide insight into CXCL16 T123V181 haplotypes as a novel biomarker for improving the early identification of high risk for traumatic sepsis or MODS." (PMID 34539750, 2021). "To date, there is little information regarding the clinical relevance of CXCL16 polymorphisms in trauma patients with sepsis and MODS." (PMID 34539750, 2021). "In this study, we selected a set of tagging single nucleotide polymorphisms (tag SNPs) in the CXCL16 gene and investigated their clinical relevance to the development of sepsis and multiple organ dysfunction syndrome (MODS) in patients with major trauma in three independent Chinese Han populations." (PMID 34539750, 2021). "Only CXCL16 T123V181 haplotype was associated with an increased risk for sepsis morbidity and higher MOD scores in the three cohorts (OR = 1.89, P = 0.001 for the Chongqing cohort; OR = 1.76, P = 0.004 for the Zhejiang cohort; OR = 1.55, P = 0.012 for the Guizhou cohort)." (PMID 34539750, 2021). "Sepsis‐trained resident macrophages released a chemokine network including CXCL16 triggers tissue residency of T cells via CCR2 and CXCR6 stimulations responsible for decreased risk of tumor development after sepsis cure." (PMID 39494816, 2024). "In this report, we present experimental evidence for the impact of two missense tag SNPs of CXCL16 on sepsis and MODS." (PMID 34539750, 2021). "Chemokine C-X-C motif ligand 16 (CXCL16) plays an important role in the occurrence and development of sepsis through leukocyte chemotaxis, leukocyte adhesion and endotoxin clearance." (PMID 34539750, 2021). "Second, it is difficult to obtain additional blood samples to detect the serum level of CXCL16 in patients with sepsis." (PMID 34539750, 2021). "We selected a set of tag SNPs within the entire CXCL16 gene and investigated their clinical relevance in relation to the development of sepsis and MODS in patients with major trauma in three independent Chinese Han populations." (PMID 34539750, 2021). "Our study confirms the relevance of RAGE, Ang-2, IL-1RA and SP-D, and is novel supporting the inclusion of CXCL16, in BMs panels for predicting ARDS diagnosis and ARDS and sepsis outcome." (PMID 34811434, 2021). "We demonstrate the mechanism of CXCL16 T123V181 haplotype which regulates the sepsis morbidity rate and thus provide a new biomarker for early diagnosis of sepsis and MODS." (PMID 34539750, 2021). "In addition, in a prospective study enrolled of 232 sepsis patients, the AUC of combination of PaO2/FiO2, RAGE, SP-D, AngII and CXCL16 was 0.881 (95% CI: 0.837−0.925), and in Lorraine's research, AUC of multivariable model (includes SPD, RAGE, IL-8, CC16, IL-6) was 0.750 (95% CI: 0.700−0.840)." (PMID 39319361, 2024).
asthma (6 papers, 2009 to 2025). "In the future, the correlation between polymorphisms in CXCL16 patients and the degree of asthma disease in asthma patients will be evaluated, and the mechanism of how CXCL16 affects MHC II will be further studied." (PMID 40050290, 2025). "Therefore, further asthma patient cohort research is required to investigate whether CXCL16 polymorphism can lead to DC dysfunction and alleviate asthma airway inflammation." (PMID 40050290, 2025). "To further investigate the role of CXCL16 in Aspergillus-induced asthma, we used CXCL16-knockout mice and WT littermates induced by Aspergillus to observe the airway hyperresponsiveness and overproduction of mucus." (PMID 40050290, 2025). "Then, we calculated the mRNA expression of CXCL16 in each cell cluster of asthma lung, and we found that the mRNA expression of CXCL16 in DCs and endothelial cells were increased in mice asthma model." (PMID 40050290, 2025). "To explore the role of CXCL16 in the pathogenesis of asthma, we first clarified the localization of CXCL16 and assessed the distribution of CXCL16-positive cells in the lung tissue." (PMID 40050290, 2025). "We further identified CXCL16 expressed increased in DCs of the asthma lung by flow cytometry and western blot assay." (PMID 40050290, 2025). "Lung Cell Atlas scRNA-seq dataset of asthma patients was used to show the expression of CXCL16+ cells in lung tissue." (PMID 40050290, 2025). "Our results demonstrated that CXCL16 is mainly expressed in DCs in asthma patients and asthma mouse models by scRNA-seq data." (PMID 40050290, 2025). "The location of CXCL16 in types of cells that participate in the development of asthma airway inflammation has been reported as controversial." (PMID 40050290, 2025). "Our results highlight the vital role of the CXCL16 in dendritic cells in antigen processing and presentation in asthma airway inflammation." (PMID 40050290, 2025). "We found that CXCL16 predominated distributed in DCs, activated DCs, and luminal macrophage in asthma patients." (PMID 40050290, 2025). "We found that CXCL16 is mainly expressed on DCs in the lung tissues of asthma patients and asthma mice." (PMID 40050290, 2025). "Targeted drugs and inhibitors that inhibit CXCL16 will be a very meaningful treatment approach for CXCL16 wild-type genotype individuals who suffer from asthma." (PMID 40050290, 2025). "In asthma airway inflammation, dendritic cells express a high level of CXCL16 under the condition of DC maturation and proinflammatory stimulation." (PMID 40050290, 2025). "CXCL16 knockout led to the suppression of airway inflammation, mucus overproduction, and airway hyperresponsiveness in Aspergillus-induced asthma." (PMID 40050290, 2025). "The differentially expressed genes included those related to inflammation (CCL22, CXCL16, AREG, MMP12) involved in asthma pathophysiology, as well as genes associated with the skin barrier (IVL, CDSN, SPINK5, FLG)." (PMID 39451560, 2024). "We have detected relatively high concentrations of CXCL16 in bronchoalveolar lavage compared to other chemokines from both normal subjects and patients with asthma and sarcoidosis, which implies a constitutive expression of CXCL16 by cells in the lung." (PMID 19415545, 2009). "In asthma patients, CXCL16 is expressed in airway epithelial cells and alveolar macrophages." (PMID 40050290, 2025). "To explore whether CXCL16 knockout alters the expression of costimulatory cell surface molecules in response to Aspergillus-induced asthma, we detected the expression of CD80 and CD86 of the DCs in lung tissue cells for flow cytometry." (PMID 40050290, 2025). "The study suggested that inhibition of CXCL16 can be a potential therapy for asthma." (PMID 40050290, 2025).